PDCD1 (programmed cell death 1)
Diseases named in the same sentence as PDCD1 in open-access papers (continued):
Sharing a sentence is not in itself a finding about the gene and the disease.
glioma (84 papers, 2017 to 2026). A benign or malignant brain and spinal cord tumor that arises from glial cells (astrocytes, oligodendrocytes, ependymal cells). "Genes associated with PDCD1 are implicated in the inflammatory immune response and T-cell-mediated immune response in glioma." (PMID 38660136, 2024). "Other studies have similarly demonstrated increased CD68+ cells in the rGBM microenvironment when comparing pre- and post-treatment glioma samples and found it may be associated with decreased efficacy of immune checkpoint inhibitors, such as pembrolizumab anti-programmed cell death 1 (PD-1)." (PMID 39409905, 2024). "After that, we found that 6 immune checkpoints (CD274, CTLA4, LAG3, LGALS9, PDCD1, and PDCD1LG2) were significantly upregulated in the high-glioma-risk group, while RDH5, RDH10 and DHRS3 simultaneously have a substantial positive connection with PDCD1LG2." (PMID 39465792, 2024). "We found a strong expression of most immune checkpoints, including PDCDL1 and PDCD1, in tumor cells of glioma samples overexpressing HEC1." (PMID 39021287, 2024). "In general, gliomas had lower transcript expression of SIRPA (gene encoding SIRPalpha) and higher of PD-L1 (CD274), PD-L2 (PDCD1LG2), TIM-3 (HAVCR2), PD-1 (PDCD1) (respectively)." (PMID 36768201, 2023). "All six of the most critical ICGs that were examined, including CD274, CTLA4, HAVCR2, IDO1, PDCD1, and PDCD1LG2, exhibited a significant positive correlation with the risk scores in glioma samples." (PMID 36845382, 2023). "Based on the TCGA and CGGA datasets, we proved that PTX3 positively correlated with CD276, CD274, PDCDL1LG2, HAVCR2, CD80, IDO1, and PDCD1 in pan‐glioma, GBM, and LGG." (PMID 35855654, 2022). "In CGGA dataset, PDIA5 expression was positively associated with CD276, CD274, PDCD1LG2, and HAVCR2 in pan-glioma and LGG patients, and positively correlated with CD276, PDCD1, CD274, PDCD1LG2, and HAVCR2 in GBM patients." (PMID 33664747, 2021). "The upregulation of the programmed cell death 1(PD-1)/programmed death-ligand 1 (PD-L1) axis is one of the key contributors to immunosuppression in glioma TME." (PMID 33810532, 2021). "We also simultaneously disrupted endogenous PD-1 (PDCD1), thereby averting the potential effects of post-treatment PD-L1 upregulation in gliomas that was observed in the clinical trial." (PMID 31727131, 2019). "The presence of immunosuppressive signals, such as activation of the programmed cell death-1 (PD-1) pathway and the release of cytokines with immune-inhibitory properties by glioma and immune cells, contributes to the malignant phenotype and poor prognosis of these tumors." (PMID 40580238, 2025). "Rad_score was positively correlated with glioma‐related genes, such as PDCD1, CD27, and CD70." (PMID 39030882, 2024). "Notably, we also found that 6 immune checkpoints were significantly upregulated in the high-glioma-risk group, including CD274, CTLA4, LAG3, LGALS9, PDCD1, and PDCD1LG2." (PMID 39465792, 2024). "Disordered genes, such as PDCD1, are related to the pathological progression of gliomas." (PMID 39555702, 2024). "The high-risk group presented a higher expression of PD1 (PDCD1), CTLA4, PD-L1 (CD274), and PD-L2 (PDCD1LG2), and our risk signature could also distinguish glioma patients with similar expression levels of immune checkpoints." (PMID 37004060, 2023). "Patients with high PDCD1 expression in their tumors had shorter survival than patients with low PDCD1 expression in their tumors according to both the Chinese Glioma Genome Atlas (CGGA) and Gene Expression Profiling Interactive Analysis (GEPIA) of The Cancer Genome Atlas (TCGA)." (PMID 36591276, 2022). "It was evident that SIGLEC15, LAG3, and PDCD1 were highly expressed in glioma." (PMID 35663965, 2022). "Moreover, efficacy of programmed cell death 1/programmed death ligand 1(PD1/PD-L1) inhibitors has been reported in preclinical glioma models and in individual human cases." (PMID 35928223, 2022).
glioma (continued). "Very recently and for the first time in solid tumors, study on a recombinant anti-EGFRvIII CAR T-cell through co-disruption of TRAC, ß2 M and PDCD1 genes by means of CRISPR-Cas9 showed higher anti-glioma activities compared to previous anti-EGFRvIII CAR T-cell therapies." (PMID 32973401, 2020). "CS nanocapsules were delivered intranasally for RNA interference (RNAi) mediated knockdown of galectin-1 in GL261 mouse glioma line, and demonstrated successful nose-to-brain transport of siRNA along with survival benefits when delivered with programmed cell death-1 (PD-1) immunotherapy in vivo." (PMID 32849207, 2020). "We also observed positive correlations between the risk score and several immune checkpoint genes, including SIGLEC7, PDCD1, LILRB2, HAVCR2, and LAG3, which have been tied to poor prognosis in glioma." (PMID 41180518, 2025). "The PD-L1/PD-1 axis (CD274/PDCD1) and CTLA4 are currently considered core targets in glioma immunotherapy." (PMID 40661083, 2025). "Our data revealed a significant correlation between the expression levels of immune checkpoint molecules (CD274, CTLA4, HAVCR2, LAG3, PDCD1, PDCD1LG2, TIGIT, and SIGLEC15) and RAB32 in high-grade gliomas (HGG)." (PMID 39668831, 2024). "Signature scores of immune checkpoints, including CTLA4, LAG3, PDCD1, PD-L1, PD-L2 and TIGIT as well as the top five marker genes within each TAM subset were calculated using RNA-seq data from TCGA low grade glioma patients." (PMID 38515213, 2024). "Assessments of the immune blockade response to 3 checkpoints (PDCD1, CD274, and PDCD1LG2) and the IC50 for 2 classical antitumor drugs were conducted for glioma samples with varying SOCS1 expression levels in the CGGA and TCGA databases." (PMID 39654174, 2024). "The expression of the more well-known immune-related targets in glioma, such as CTLA4, PDCD1 (PD-1), CD274 (PD-L1), LAG-3, and CD47, was then examined." (PMID 38396140, 2024). "We found that cluster 2 had a remarkably high expression level of most of the immune checkpoints including PD-1 (PDCD1), PD-L1 (CD274), and CTLA-4 (CD276), and most of these trends were consistent between IDH-mutant and IDH-wildtype gliomas." (PMID 36970537, 2023). "In general, most immune checkpoints (including PD-1, TIM-3, CD96, PDCD1, IDO1, PDCD1LG2, and CTLA-4) were highly expressed in glioma cells." (PMID 36778644, 2023). "We further analyzed the expression distribution of immune checkpoints gene (including CD274, CTLA4, HAVCR2, LAG3, PDCD1, PDCD1LG2, TIGIT, and SIGLEC15) in glioma tissues and normal brain tissues using the TCGA database." (PMID 36915038, 2023). "We investigated the immune checkpoint expression in glioma specimens and uncovered that CD274 (PD-L1), PDCD1, PDCD1LG2, CTLA4, CD276, HAVCR2, and LAG3 were significantly overexpressed in the high DDR score subtype." (PMID 35720326, 2022). "PIMREG correlated with CTLA-4, PDCD1, LAG3 and other immune checkpoints in glioma and correlated with the patient’s response to immunotherapy." (PMID 35928818, 2022). "We further explored the relationship between ITGA5 and some immune checkpoints, such as PDCD1 (PD-1), CD274 (PD-L1), and PDCD1LG2 (PD-L2) in gliomas based on the TCGA dataset." (PMID 35371978, 2022). "The highest expression was detected in the WHO glioma grade IV tumors (CD274 p = 2.0e − 08, HAVCR2 p = 1.5e − 09, LAG3 p = 9.7e − 05, PDCD1 p = 5.6e − 05, PDCD1LG2 p = 2.2e − 18, and SIGLEC15 p = 4.3e − 05)." (PMID 35198632, 2022). "Moreover, PAX3 expression demonstrates significant positive correlations with multiple immune checkpoints, particularly PDCD1, SIGLEC7, and LILRB2, underscoring its involvement in immune regulation within the glioma microenvironment." (PMID 41180518, 2025). "However, MAPKAPK2 is positively correlated with a series of immune regulators such as CD274, CD276, PDCD1, and CD70, which probably affect the tumor killing effect of the infiltrated immune cells in glioma tissue." (PMID 38322416, 2024).
glioma (continued). "Moreover, the high/low radiomics scores were highly correlated with the known glioma‐related genes, including CD70, CD27, and PDCD1." (PMID 39030882, 2024). "Specifically, we found that, as IGFBP5 levels increased, the expression of the seven immune checkpoint genes (BTLA, CD274, CTLA4, HAVCR2, LAG3, PDCD1, and PDCD1LG2) were increased and a large positive correlation was observed between IGFBP5 and these immune checkpoints in glioma." (PMID 38164271, 2024). "Indeed, the expression of A3C displayed positive correlations with CD274, PDCD1, PDCD1LG2, SIGLEC15, CTLA4, HAVCR2, and GZMB in glioma (P < 0.05)." (PMID 37809064, 2023). "The gene expression of PDCD1 and CD274 were mainly located in the T cell cluster in glioma." (PMID 37441589, 2023). "The corresponding value of PDCD1 and LAG3 has also been demonstrated in successive glioma studies." (PMID 35896732, 2022). "Correspondingly, it showed that CD101 expression could potentially interact with numerous immune-relevant genes, including CD276, CD274, CD80, CTLA4, and PDCD1, implying an immunoregulatory role of CD101 in the glioma immune microenvironment." (PMID 35350788, 2022). "Given that, we hypothesized that NK CD56bright, Tfh, and macrophage cell types might be closely related to immune regulation in TME of glioma, and B7H3, PDCD1, LAG3 and CXCL16, CXCR4, CCR5 might be key targets for glioma immunotherapy." (PMID 35896732, 2022). "The immune checkpoints, including CD274 and PDCD1, were significantly differentially expressed between the two groups, and the TIDE score and exclusion score were significantly different between the two groups, which provides a preliminary basis for glioma immunotherapy." (PMID 36552760, 2022). "The immune checkpoints, including CD274 and PDCD1, were significantly differentially expressed between the two groups, and the TIDE score and exclusion score were significantly different between the two groups, which provides a preliminary basis for immunotherapy of glioma." (PMID 36552760, 2022). "Fortunately, the expression levels of PDCD1 (PD-1), CD274 (PD-L1), and CTLA4, the vital immune checkpoints in glioma, were significantly higher in IS2 than other subtypes, which indicated that patients receiving ICIs therapies might achieve a better curative effect." (PMID 34404444, 2021). "Results refer thatMLLT11 had a highly negative correlation with PDCD1, PD-L1, TIM3(HAVCR2), and PD‐L2 (PDCD1LG2) in grade 3 glioma analysis." (PMID 36033495, 2022).
gastric cancer (74 papers, 2016 to 2026). A primary or metastatic malignant neoplasm involving the stomach. "Programmed cell death 1 (PD-1) blockade is effective in immunotherapy of various tumors, but may cause hyperprogressive disease in immunotherapy of advanced gastric cancer." (PMID 34167561, 2021). "In recent years, immunotherapy has become a significant adjuvant treatment for gastric cancer, with programmed cell death-1 (PD-1) inhibitors emerging as an effective option, particularly for advanced or metastatic cases." (PMID 40176817, 2025). "Previous research has demonstrated that CTLA4 and PDCD1 are biomarkers with high expression levels in gastric cancer tissues." (PMID 38693422, 2024). "This overexpression also enhances the expression of immune checkpoint proteins, CTLA4 and PDCD1, ultimately inhibiting immunotherapy targeting gastric cancer cells." (PMID 38693422, 2024). "Although nivolumab (anti-programmed cell death-1 antibody) is a promising approach for advanced gastric cancer (AGC), the response rate remains limited." (PMID 34980017, 2022). "Immune checkpoint inhibitors (ICIs) such as anti-programmed cell death-1 (PD-1) or programmed cell death ligand-1 (PD-L1) monoclonal antibodies have prolonged survival in various types of malignancies, including advanced gastric cancer (AGC)." (PMID 35205802, 2022). "Immunotherapies targeting programmed cell death 1 (PD-1) and programmed death-ligand 1 (PD-L1) have been approved for gastric cancer (GC) patients." (PMID 32226313, 2020). "Finally, we verified in vitro that DLX2 in gastric cancer cells can affect the expression of PDCD1 on the surface of T cells." (PMID 41244921, 2025). "Programmed death ligand 1 (PD-L1) expression as a predictive biomarker for programmed cell death 1 (PD-1) inhibitor efficacy in gastric cancer (GC) remains controversial." (PMID 31285589, 2019). "A number of T cell co-inhibitory molecules CTLA4, ICOS, CD274, PDCD1, and IDO were markedly downregulated by NPRL2 treatment which was in agreement with the data found in bioinformatics analysis in stomach cancer patients' samples." (PMID 39932765, 2025). "Lastly, BAX showed positive correlations with several immune inhibitors, including PDCD1 and TIGIT in gastric cancer." (PMID 40652278, 2025). "Experiments in vitro and in vivo demonstrated that METTL1 enhances gastric cancer cell activity by suppressing T cell proliferation and upregulating CTLA4 and PDCD1." (PMID 38693422, 2024). "IL-18 promotes the immune escape of gastric cancer cells by upregulating programmed cell death 1 (PD1) in NK cells, downregulating CD70 in tumor cells and inhibiting the CASP8-mediated apoptosis in gastric cancer cells." (PMID 37833958, 2023). "The immune checkpoint analysis indicated that gastric cancer patients with upregulated GGT5 expression showed a higher TIDE score and expression of CD274, CTLA4, HAVCR2, LAG3, PDCD1, PDCD1LG2, and TIGIT than patients in the GGT5-low expression group." (PMID 35368661, 2022). "The research results indicated that there exists a significant positive correlation between DLX2 and CTLA4, PDCD1, HAVCR2 and TIGIT, which may contribute to the gastric cancer cells’ ability to evade immune system attacks." (PMID 41244921, 2025). "Programmed cell death 1 (PD1) inhibitors have shown promising treatment effects in advanced gastric cancer, the beneficiary population not definite." (PMID 35073519, 2022). "Currently, there are several targeted drugs approved for the treatment of gastric cancer, including the first-line trastuzumab for HER2+ patients, the second-line VEGFR2 antagonist remucirumab and the third-line programmed cell death 1 (PD1) inhibitors nivolumab and pembrolizumab." (PMID 34719320, 2022). "Here, we identified a protumorigenic subset of macrophages that constitutively expressed programmed cell death 1 (PD1) and accumulated in advanced-stage gastric cancer (GC)." (PMID 29799520, 2018).
gastric cancer (continued). "Immune checkpoint inhibitors (ICIs) targeting programmed cell death 1 (PD-1) and its ligand PD-L1 have revolutionized the treatment of various solid tumors, including non-small cell lung cancer (NSCLC) and gastric cancer (GC)." (PMID 38774209, 2024).
colorectal cancer (72 papers, 2015 to 2026). A primary or metastatic malignant neoplasm that affects the colon or rectum. "We evaluated 88 high-frequency microsatellite instability (MSI-H) colorectal cancers and analysed the function of the identified neoantigenic mutations and their influence on programmed cell death 1 (PD-1) blockade efficacy." (PMID 36732592, 2023). "Tumor CD274 expression level was inversely associated with the amount of F. nucleatum in colorectal cancer tissue, suggesting that different immunosuppressive mechanisms (i.e. PDCD1 immune checkpoint activation and tumor F. nucleatum enrichment) tend to be used by different tumor subgroups." (PMID 37538192, 2023). "To illustrate the correlation of PDCD1 and IFN-I in human cancer patients, we analyzed the cellular source of PDCD1 in colorectal cancer patients." (PMID 38995014, 2024). "For example, immunotherapy based on immune checkpoint blockade of programmed cell death-1 (PD-1) and its ligand-1 (PD-L1) for colorectal cancer treatment has yielded promising results." (PMID 38149207, 2023). "Loss of ARID1A was found to have a significant correlation with the expression of IFN-γ and checkpoint genes (including PD-L1, CTLA4, and PDCD1) in microsatellite-stable colorectal cancer." (PMID 35198440, 2022). "IFNG and HAVCR2 gene expression, which were augmented, best defined Th1-like T cells in colorectal cancer, while PDCD1, an immune checkpoint inhibitor, was decreased." (PMID 31191543, 2019). "For instance, METTL14 may promote CD8+ T-cell dysfunction in colorectal cancer through stabilization of Ebi3 mRNA, yet enhance T-cell activation in other contexts by facilitating PDCD1 mRNA degradation." (PMID 41164187, 2025). "Furthermore, a positive correlation was observed between the expression of CDKN2A and various immune checkpoint genes in colorectal cancer, namely PDCD1, CTLA-4, and CD274." (PMID 37950153, 2023). "Genetic variations in the PDCD1 were also investigated in colorectal cancer." (PMID 33519815, 2020). "Targeting programmed death 1 ligand 1 (PD-L1) or its receptor PD-1 (programmed cell death 1) has promising curative effects in several tumors with frequent RAS mutations such as non-small cell lung cancer (NSCLC) and mismatch-repair-deficient colorectal cancer." (PMID 37434177, 2023). "We determined that the expression level of PDCD1 is positively correlated with the levels of IFNB1 and IFNAR1 in myeloid cells in human colorectal cancer." (PMID 38995014, 2024). "We report here that the PDCD1 transcription level exhibits a positive correlation with the IFNB1 and IFNAR1 level in myeloid cells in human colorectal cancer patients." (PMID 38995014, 2024). "In colorectal cancer, phosphorylated CTD interacting factor 1 (PCIF1) modulates colorectal cancer growth and response to anti-programmed cell death 1 (PD-1) in a context-dependent mechanism in which PCIF1 directly targets FOS, IFITM3, and STAT1 via N6,2′-O-dimethyladenosine (m6Am) modifications." (PMID 40681213, 2025). "However, we note that we only see strong evidence for a causal role of PDCD1 expression in blood (not colon tissue) on cancer risk—suggesting that the mechanism linking PDCD1 expression and colorectal cancer risk may be more complex than the presumed local effects within colorectal tissue." (PMID 40447568, 2025). "Recently a study has found that increased expression of BATF, a significant positive correlation that existed with PDCD1 expression, may suppress CD8+ T function and affect the development of colorectal cancer." (PMID 34178621, 2021). "PDCD1, PDCD1LG2 are the key targets in the treatment of widely used PD-1/PD-L1 inhibitors and plays an important role in adolescent idiopathic arthritis, diffuse large B-cell lymphoma, head and neck squamous cell carcinoma, colorectal cancer and other diseases." (PMID 33215029, 2020).
colorectal cancer (continued). "Finally, the immune checkpoints PDCD1 (PD-1) and CD274 (PDL-1) were also positively correlated with interleukin-17A mRNA expression, indicating that interleukin-17A is a promising predictor of the immunotherapeutic outcome of PD-1/PDL-1 blockade in colorectal cancer." (PMID 36098359, 2022).